GSR (glutathione-disulfide reductase)
Description:
Catalyzes the reduction of glutathione disulfide (GSSG) to reduced glutathione (GSH). Constitutes the major mechanism to maintain a high GSH:GSSG ratio in the cytosol.
Synonyms: GR; GRase; CNSHA10; GSRD; HEL-75; HEL-S-122m
Tractability: Small molecule: an approved drug acts on it; a structure with a bound ligand is known; a high-quality ligand is known; it has a high-quality binding pocket; it belongs to a druggable protein family. PROTAC: ubiquitination databases record sites on it; its protein half-life has been measured; a small molecule that binds it is known.
Target class: Enzyme; Oxidoreductase
Chemical probes: PD084163
Safety:
Unwanted effects reported when the protein is acted on. In parentheses: how it was acted on, where the effect was seen, and who reports it.
gastrointestinal toxicity (source: ClinPGx)
Gene: Protein-coding gene on chromosome 8 (30,678,064 to 30,727,975, reverse strand). Ensembl gene ENSG00000104687.
Subcellular location: Mitochondrion (Isoform Mitochondrial); Cytoplasm (Isoform Cytoplasmic)
Subcellular location (Human Protein Atlas): Cytosol; Endoplasmic reticulum
Pathways (Reactome):
Cellular responses to stimuli: Detoxification of Reactive Oxygen Species; NFE2L2 regulating anti-oxidant/detoxification enzymes
Metabolism: Interconversion of nucleotide di- and triphosphates; Metabolism of ingested H2SeO4 and H2SeO3 into H2Se
Gene Ontology:
Molecular function: glutathione-disulfide reductase (NADPH) activity; electron transfer activity; flavin adenine dinucleotide binding; NADP binding; oxidoreductase activity; oxidoreductase activity, acting on a sulfur group of donors, NAD(P) as acceptor
Biological process: cell redox homeostasis; cellular response to oxidative stress; glutathione metabolic process; cellular oxidant detoxification
Cellular component: cytosol; extracellular exosome; mitochondrion; mitochondrial matrix; cytoplasm; external side of plasma membrane
Genetic constraint (gnomAD): Loss-of-function variants: 22 observed, 26.59 expected, observed/expected ratio (o/e) 0.83, 90% interval 0.59 to 1.18. The upper end of that interval is the gene's LOEUF score, 1.18, which puts it in group 5 of 6, group 1 being the genes least tolerant of losing a copy. Missense variants: 453 observed, 413.41 expected, observed/expected ratio (o/e) 1.1, 90% interval 1.01 to 1.18. Synonymous variants: 188 observed, 158.69 expected, observed/expected ratio (o/e) 1.18, 90% interval 1.05 to 1.34.
Homologues: Orthologues: chimpanzee GSR (99% identical), macaque GSR (89% identical), dog GSR (88% identical), pig GSR (86% identical), rat Gsr (83% identical), mouse Gsr (83% identical), rabbit GSR (75% identical), tropical clawed frog gsr (71% identical), guinea pig GSR (71% identical), zebrafish gsr (55% identical), Caenorhabditis elegans gsr-1 (52% identical). Paralogues in human: TXNRD2 (38% identical), TXNRD1 (35% identical), TXNRD3 (35% identical), DLD (27% identical), AIFM3 (19% identical), AIFM1 (18% identical), PYROXD1 (15% identical).
Diseases named in the same sentence as GSR in open-access papers:
GSR is named in the same sentence as 86 diseases in open-access papers, as found by Europe PMC text mining. Sharing a sentence is not in itself a finding about the gene and the disease. The quoted sentences say what the papers report.
breast carcinoma (8 papers, 2017 to 2025). "Similarly, PHA treatments for two breast cancer cell lines induce the GSR mRNA expression associated with oxidative stress." (PMID 33807834, 2021). "Since either PHA treatment or Baf A1/PHA cotreatments induced ROS, the effects of autophagy in antioxidant gene expressions such as SOD1, NFE2L2, TXN, and GSR in breast cancer cells were assessed by real-time PCR." (PMID 35883843, 2022). "Following PHA treatment, the GSR mRNA was overexpressed in the breast cancer cells compared to control." (PMID 33807834, 2021). "The GSR mRNA expression for two PHA-treated breast cancer cell lines was examined by qRT-PCR analysis." (PMID 33807834, 2021). "GSR mRNA expression is upregulated by physapruin A-induced ROS generation in breast cancer cells." (PMID 34209212, 2021).
colorectal cancer (7 papers, 2022 to 2025). A primary or metastatic malignant neoplasm that affects the colon or rectum. "Kaplan–Meier survival analysis showed that high expression of GSR, CALM1, and MAPK9 was significantly associated with better prognosis in colorectal cancer patients." (PMID 40696679, 2025). "Glutathione reductase (GSR) was overexpressed in breast and colorectal cancers, emphasizing the role of the glutathione system in tumor survival." (PMID 39594421, 2024). "According to a recent study, AMPK1 promotes the occurrence of colorectal cancer by regulating GSR phosphorylation." (PMID 37168510, 2023). "In contrast, upregulation of GSR contributed to the tolerance of colorectal cancer cells to the acidic environment by maintaining a higher level of GSH." (PMID 36635256, 2023). "For example, GSR was found to act as an oncogene in many cancers, such as cervical cancer, hepatocellular carcinoma, and colorectal cancer." (PMID 36335337, 2022). "The results showed that, compared with normal tissues, the expression of ADRA1B, CDKN2A, FCER2, and IL13 was significantly upregulated in colorectal cancer tissues, while CALM1, CTNNA1, GSR, INSR, and MAPK9 were significantly downregulated." (PMID 40696679, 2025). "Interestingly, the decreased expression levels of ACADM, GSR and HADH were closely related to the deterioration of colorectal cancer patients (p < 0.01)." (PMID 36552870, 2022). "Therefore, we used the correlation of the expression level of genes with the prognosis of colorectal cancer patients as an evaluation index, and finally identified eight critical enzymes of amino acid metabolism in colon TAMs, namely, ACADM, ACADS, GPX4, GSR, HADH, HMGCL, HMGCS1 and IDH1." (PMID 36552870, 2022).
cervical cancer (6 papers, 2020 to 2023). A primary or metastatic malignant neoplasm involving the cervix. "Furthermore, GSR in human cervical cancer tissues was significantly upregulated, whereas GSR knockdown results in ROS-dependent cell death." (PMID 36635256, 2023). "However, when the cells were treated with PTX, this drug induced the downregulation of the ATP7A, ATP7B, CTR1, MRP-2, and GSR genes in both cervical cancer cell lines." (PMID 33680921, 2020). "Furthermore, GSR and GPX genes have already been reported as essential features to block EMT in melanoma cells, cervical cancer, hepatocellular carcinoma, gastric, pancreatic, breast, and colon cancers." (PMID 32850411, 2020).
lung carcinoma (5 papers, 2020 to 2023). "GSR depletion renders human lung cancer cells more sensitive to TXNRD1 inhibitor-Auranofin." (PMID 36635256, 2023).
colon cancer (4 papers, 2019 to 2022). "GSR was downregulated in COAD and inhibited the metastasis of colon cancer cell." (PMID 35712285, 2022).
hepatocellular carcinoma (4 papers, 2020 to 2024). A malignant tumor that arises from hepatocytes. "Critically, SLC27A5 enhances the therapeutic efficacy of sorafenib in hepatocellular carcinoma by promoting sorafenib-induced ferroptosis through inhibition of the NRF2/GSR pathway." (PMID 39633985, 2024). "MiR-214, which is upregulated in the liver of ethanol-treated rats and in a human hepatoma cell treated with ethanol, promotes oxidative stress by directly inhibiting the expression of glutathione reductase (GSR) and cytochrome P450 oxido-reductase (POR)." (PMID 38067261, 2023).
lymphoma (4 papers, 2016 to 2025). A malignant (clonal) proliferation of B- lymphocytes or T- lymphocytes which involves the lymph nodes, bone marrow and/or extranodal sites. "The main finding of this study is that by reproducing in vitro a condition of in vivo hyperCHO, lymphoma lymphoblastic cells overexpressed genes for antioxidant proteins (SOD1, SOD2, CCS, GSR, GSS and CAT) with the only exception of GRX2." (PMID 26754536, 2016). "Specifically, we discover that oxPPP-derived NADPH is necessary to drive the reactions catalyzed by TRXR and GSR, identifying inhibition of the PRPS1 isoform as a new potential therapeutic angle to sensitize cells to toxic levels of oxidative stress in these lymphomas." (PMID 39868212, 2025).
melanoma (4 papers, 2016 to 2022). A malignant, usually aggressive tumor composed of atypical, neoplastic melanocytes. "Pharmacological inhibition of GSR in melanoma cell lines has been shown to reduce proliferation, reduce migration, increase ROS, and decrease cellular GSH:GSSG ratio, suggesting the GSR function is co-opted by melanomas." (PMID 35326683, 2022). "Inhibition of GSR (Glutathione Reductase) activity induced oxidative stress, evidenced by intracellular ROS increase and peroxidation of mitochondrial membrane in melanoma cells." (PMID 27206673, 2016). "Moreover, glutathione reduction has also been reported as a key player in the induction of EMT lowering oxidative stress and enhancing metastasis in murine melanoma cells, although our cells showed a downregulation of GSR gene." (PMID 32850411, 2020). "Expressions of GPX2, GPX4, GSR, and G6PD have been found to be elevated in melanomas and other cancers." (PMID 35326683, 2022).
Obesity (4 papers, 2022 to 2025). Accumulation of substantial excess body fat. "On the contrary, DCT downregulated the obesity-induced overexpression of GSR (p < 0.05) and increased the mRNA levels of GPX-3 (p < 0.05)." (PMID 36139877, 2022). "Finally, DCTE reduced the obesity-induced alterations in the gene expression of GSR (p < 0.01), SOD-1 (p < 0.05) and PGC-1α and up-regulated the mRNA levels of GPX-3 (p < 0.05)." (PMID 36139877, 2022). "Obesity was also associated with a downregulation in the gene expression of NOX-4 (p < 0.05) and with a significant increase in the mRNA levels of GSR (p < 0.01), SOD-1 (p < 0.001) and PGC-1α (p < 0.05) in gastrocnemius muscle." (PMID 36139877, 2022). "Finally, these transgenerational studies established that obesity-induced compromise of testicular antioxidant defenses are transversal to all three generations, especially regarding glutathione-disulfide reductase (GSR) (intergenerational) and CAT levels (inter and transgenerational)." (PMID 40002337, 2025). "DCE prevented the changes in the gene expression of GSR, PGC-1α and NOX-4 (p < 0.05 for all) induced by obesity and also increased the mRNA levels of GPX-3 (p < 0.05)." (PMID 36139877, 2022). "DC only attenuated the obesity-induced downregulation of NOX-4 (p < 0.05), whereas DCE also prevented the alterations in the mRNA levels of NOX-4 (p < 0.01), GSR (p < 0.05) and GPX-3 (p < 0.01)." (PMID 36139877, 2022). "DC attenuated the reduction in the gene expression of GSR and SOD-1 (p < 0.05 for both), whereas DCE, DCT, and DCTE completely prevented the obesity-induced reduction in the mRNA levels of NOX-4, GSR, GPX-3 and SOD-1 (p < 0.05)." (PMID 36139877, 2022). "Obesity induced a significant decrease in the mRNA levels of NOX-4 (p < 0.05), GSR (p < 0.01), GPX-3 (p < 0.05), and SOD-1 (p < 0.05)." (PMID 36139877, 2022). "Moreover, supplementation with CTE prevented the obesity-induced decrease in the gene expression of the antioxidant enzymes GPX-3, GSR and SOD-1, and increased the mRNA levels of endothelial nitric oxide synthase (eNOS) in arterial tissue." (PMID 36009292, 2022).
schizophrenia (4 papers, 2018 to 2024). A major psychotic disorder characterized by abnormalities in the perception or expression of reality. "The ketosis gene expression profile was partially discordant with schizophrenia and bipolar disorder and entirely discordant with major depressive disorder, showing significant downregulation of the genes G6PD, GSR, and RPIA." (PMID 39125835, 2024).
COVID-19 (3 papers, 2021 to 2025). A disease caused by infection with severe acute respiratory syndrome coronavirus 2. "Serum from patients with severe COVID-19 significantly upregulated genes involved in the cellular antioxidant response in HUVEC, including NFE2L2, HMOX1, SOD1, CAT, GPX1, and GSR." (PMID 41583455, 2025). "SOD1 and GSR showed decreased levels of gene expression in the placentas of both COVID-19 groups compared to controls, though not significantly." (PMID 34679654, 2021).
glioblastoma (3 papers, 2022 to 2025). The most malignant astrocytic tumor (WHO grade IV). "An increase in the mRNA expression of SOD2, GSR, and GPX4 was observed only in the MDR glioblastoma cell line, while CAT mRNA expression levels remained unchanged upon treatment with 2 and 5 in both cell lines." (PMID 41471777, 2025).
glioma (3 papers, 2021 to 2023). A benign or malignant brain and spinal cord tumor that arises from glial cells (astrocytes, oligodendrocytes, ependymal cells). "Overexpression of GSR decreases ROS levels, thereby promoting glioma resistance to TMZ." (PMID 38130720, 2023).
hearing loss (3 papers, 2017 to 2025). "CpG cites in hearing loss candidate genes, KCNQ1, TMEM43, GSTM1, TCF25, and GSR, were found to be highly methylated in presbycusis patients as compared to the controls." (PMID 40428348, 2025).
intracerebral hemorrhage (3 papers, 2022 to 2025). A cerebrovascular disorder characterized by bleeding into one or both cerebral hemispheres including the basal ganglia and the cerebral cortex. "We found significant overlap with gene lists associated with intracerebral hemorrhage (ICH) volume (SERPINB1, TSPO, and GSR) and absolute perihematomal edema (PHE; TSPO and GSR) volume in ICH patients." (PMID 41353157, 2025). "Dauricine also attenuated secondary brain injury after intracerebral hemorrhage by up-regulating the co-expression of GPX4 and glutathione reductase (GSR) to inhibit neuronal ferroptosis." (PMID 35481263, 2022).
leukemia (3 papers, 2016 to 2021). A malignant (clonal) hematologic disorder, involving hematopoietic stem cells and characterized by the presence of primitive or atypical myeloid or lymphoid cells in the bone marrow and the blood. "In the present study, we observed that DS and DS/Cu sharply reduced the protein level of Nrf2 both in vitro and in vivo in leukemia stem-like cells, as well as blocked the expression of Nrf2 target genes such as NQO1, GSR, and HO-1." (PMID 28518151, 2017).
prostate carcinoma (3 papers, 2021 to 2025). A carcinoma that arises from epithelial cells of the prostate gland. "The observation that MMTSO caused downregulation of GCLC, GSR, and NQO1 genes provides evidence that MMTSO could play a role in oxidative stress and antioxidant defense of prostate cancer." (PMID 40059483, 2025).
anaemia (2 papers, 2014 to 2022). "Using the ConSurf server, it was observed that highly deleterious nsSNPs with high conservation scores were located in highly conserved regions, therefore increasing the risk of hereditary anaemia by altering the GSR protein sequence." (PMID 35361806, 2022).
Anxiety (2 papers, 2021 to 2022). Intense feelings of nervousness, tension, or panic often arise in response to interpersonal stresses. "Finally, 0.35 mM sodium benzoate induced anxiety—like larval behaviour (thigmotaxis) and oxidative stress by upregulation of glutathione reductase (GSR) expression." (PMID 34578818, 2021).
asthma (2 papers, 2022 to 2025). "In particular, three ADE genes, which can be considered common susceptibility genes to asthma, such as glutathione-disulfide reductase (GSR), EPHX1, and GPX1, highlighted a relevant interaction in both variants of asthma in men and women (except for the GPX1 gene in nonallergic asthma in women)." (PMID 41154690, 2025).
bladder cancer (2 papers, 2021). "Similarly, WFA upregulates the mRNA expression of antioxidant genes (NFE2L2, CAT, SOD1, TXN, GSR, NQO1, and HMOX1) in bladder cancer cells associated with oxidative stress generation." (PMID 34209212, 2021).
diabetes (2 papers, 2014 to 2020). "Moreover, it was noted that a single treatment of alloxan processed a reduction in the action of the liver (SOD, GSR, GPX, GST, and GR) throughout the advancement of alloxan induced diabetes mellitus." (PMID 25114914, 2014).
HIV-1 infection (2 papers, 2016 to 2017). The type species of lentivirus and the etiologic agent of acquired immunodeficiency syndrome (AIDS). "Inability to induce substantial upregulation of GSR further explains disruption in the compensatory mechanism in the brain tissue samples derived from individuals with HIV-1 infection." (PMID 27335804, 2016). "HIV-1 infection decreases the abundance of mitochondrial ion channels (VDAC1, VDAC2) and glutathione reductase (GSR), which respectively facilitates the survival of infected cells and protects late stages of virus production." (PMID 28075409, 2017).
infertile (2 papers, 2022 to 2024). "PRDX5 and SOD2 were significantly underexpressed, while GSR was overexpressed in the proteomics analysis, and bioinformatics indicated a general downregulation of mitochondrial activity in the infertile group." (PMID 39726694, 2024).
neuroblastoma (2 papers, 2018 to 2022). Neuroblastoma (NB) is the most common solid, extracranial childhood tumor. "In SH-SY5Y neuroblastoma cells, the 3′-UTR of NFE2L2 is targeted by miR-153, miR27a, and miR-142-5p, with a consequent decrease in Gclc glutamate-cysteine ligase (GCLC) and glutathione-disulfide reductase (GSR) expression levels." (PMID 29643973, 2018).
osteoporosis (2 papers, 2023 to 2025). A condition of reduced bone mass, with decreased cortical thickness and a decrease in the number and size of the trabeculae of cancellous bone (but normal chemical composition), resulting in increased fracture incidence. "Their findings suggest that GSR gene polymorphisms may reduce the risk of osteoporosis." (PMID 41550870, 2025). "The analyzed polymorphisms belonging to a wide variety of genes, e.g., SOD, PON, GPx, GST, TXN, CAT, ALOX12, GSR, and NOS, focused on BMD variation, which is the current clinical gold standard for analyzing reductions in bone mass and diagnosing osteoporosis." (PMID 37107290, 2023).
ovarian carcinoma (2 papers, 2021 to 2024). A malignant neoplasm originating from the surface ovarian epithelium. "miR-214 offers protection against oxidative damage by targeting GSR and cytochrome P450 oxidoreductase (POR) and is involved in cell survival, embryonic development, and ovarian cancer resistance." (PMID 39334761, 2024).
Sepsis (2 papers, 2022 to 2025). Sepsis is defined as life-threatening organ dysfunction caused by a dysregulated host response to infection. "It exerts its inhibitory role by regulating the GSS/GSR complex, highlighting its significance in modulating ferroptosis-related pathophysiological mechanisms across various diseases, including sepsis." (PMID 40264754, 2025). "Pretreatment with the nutraceutical prevented the effects of sepsis on GPx and Alox-5 (p < 0.05 for both), but not on GSR and SOD-1 mRNA levels." (PMID 35795581, 2022).
type 2 diabetes (2 papers, 2021 to 2022). "Glutathione-disulfide reductase, also known as glutathione reductase (GR), is considered a marker of antioxidant defense in patients with type 2 diabetes." (PMID 36034923, 2022).
abortion (1 paper, 2025). the ending of pregnancy by removing a fetus or embryo before it can survive outside the uterus. "These insights suggest that oxidative stress-induced senescence plays a critical role in recurrent spontaneous abortion, with UCP2 and GSR as promising biomarkers and therapeutic targets to improve endometrial health and reduce miscarriage risk." (PMID 41387654, 2025).
alcoholic liver diseases (1 paper, 2022). A disorder caused by damage to the liver parenchyma due to alcohol consumption. "In addition, ginseng Huang jiu could improve alcoholic liver disease by regulating the GSTP1, HRAS, AKR1B1, GSTA1, Androgen receptor (AR), GSR, and LDHB genes through bioinformatics analysis." (PMID 36034901, 2022).